TTR (transthyretin)
Diseases named in the same sentence as TTR in open-access papers (continued):
Sharing a sentence is not in itself a finding about the gene and the disease.
amyloidosis (continued). "Although much more work is needed, these findings would open the possibility of designing new potential therapeutic agents against TTR-related amyloidoses." (PMID 25086037, 2014). "TTR-associated familial amyloid polyneuropathy (TTR-FAP) is the most common type, in which amyloid depositions in peripheral nerves lead to a progressive sensorimotor and autonomic neuropathy." (PMID 25471118, 2014). "Recently developed siRNA and ASO therapies, however, inhibit both MT TTR and WT TTR, because WT TTR also contributes to the formation of amyloid in FAP, especially after LT." (PMID 25228988, 2014). "Using a Drosophila model for TTR-associated amyloidosis, we found a new role for SAP as a protective factor in inhibition of TTR-induced toxicity." (PMID 23390551, 2013). "Wild‐type or mutant forms of the plasma protein transthyretin (TTR) are amyloidogenic in senile systemic amyloidosis (SSA) or familial TTR (ATTR) amyloidosis." (PMID 23537813, 2013). "Transthyretin (TTR) amyloidosis is a systemic disorder characterized by the extracellular deposition of amyloid fibrils composed of TTR, a plasma transport protein for thyroxine and vitamin A that is produced predominantly by the liver." (PMID 23425518, 2013). "One of the earliest studies in this area was performed by Robinson and co-workers who used ESI–MS to identify inhibitors of transthyretin (TTR) amyloidosis." (PMID 23063533, 2013). "This ongoing survey seeks to gather information on patients diagnosed with TTR amyloidosis to better understand this rare disease." (PMID 23425518, 2013). "TTR amyloidosis, including TTR-FAP, presents in many different forms, with considerable phenotypic variation across individuals and geographic locations." (PMID 23425518, 2013). "When the phenotypic expression of TTR amyloidosis is exclusively or predominantly cardiac, the situation is far more challenging." (PMID 23425518, 2013). "These forms of TTR-related amyloidosis are characterized by deposition in several organs including the intestine, the vitreous body of the eye, and particularly along peripheral nerves." (PMID 23390551, 2013). "The data reported here allowed us to correlate tetramer stabilization and aggregation inhibition with structural features that are important for the identification of novel lead compounds for the prevention of TTR-related amyloidoses." (PMID 23466880, 2013). "Given its phenotypic unpredictability and variability, transthyretin amyloidosis can be difficult to recognize and manage." (PMID 23425518, 2013). "TTR immunolabeling of the amyloid deposits can identify the disease as TTR amyloidosis but cannot distinguish wild-type from hereditary forms." (PMID 23425518, 2013). "Among genes with the same expression pattern in both strains after CMS, we observed robust upregulation of Ttr gene coding transthyretin involved in amyloidosis, seizures, stroke-like episodes, or dementia." (PMID 22836882, 2013). "Here we have demonstrated that TTR, which is well recognized in the etiology of certain types of amyloidoses, also forms annular oligomers." (PMID 22984597, 2012). "The transthyretin amyloidoses are characterized by the extracellular deposition of aggregates formed by the plasmatic homotetrameric protein transthyretin (TTR) in peripheral nerves and the heart." (PMID 23242152, 2012). "One of the therapeutic strategies for TTR-related amyloidosis aims at stabilizing the TTR tetrameric fold using small molecules which can either i) bind the T4 binding central channel or ii) bind outside the T4 binding channel." (PMID 23028965, 2012). "Based on the current understanding of the pathogenesis of TTR amyloidosis, it is considered that the inhibition of amyloid fibril formation by stabilization of TTR in native tetrameric form is a viable approach for the treatment of TTR amyloidosis." (PMID 22973437, 2012). "Further it has also been shown that binding of single molecule is sufficient for stalling the process of TTR amyloidosis." (PMID 22973437, 2012).
amyloidosis (continued). "The intravenously administered, lipid nanoparticle (LNP)-formulated chemically unmodified siRNA ALN-TTR02 targets the mutant TTR protein responsible for TTR-mediated amyloidosis." (PMID 22989709, 2012). "Another is transthyretin amyloidosis, in which mutant transthyretin, a protein that normally transports thyroid hormone and vitamin A, aggregates in the form of amyloid deposits in the heart, kidney, nerves and intestines." (PMID 24278740, 2012). "Regarding TTR-related amyloidosis, it has also been demonstrated, “in vitro” and “ex vivo”, that EGCG binds to TTR and increases its tetramer conformational stability." (PMID 22253829, 2012). "AD and the TTR amyloidoses share age dependence and are manifested as both autosomal dominant, mutation-related and sporadic (wild type protein associated) diseases." (PMID 22112803, 2011). "Unlike Alzheimer's disease, another common amyloidosis, localized TTR-derived amyloid in the central nervous system is rarely reported." (PMID 21179560, 2010). "Familial amyloidosis with polyneuropathy (FAP, OMIM +176300) is a fatal autosomal dominant disease caused by mutations in the TTR gene." (PMID 20840742, 2010). "Familial forms of TTR-related amyloidosis are inherited in an autosomal dominant manner and arise from single point mutations in the coding sequence of the gene." (PMID 21179560, 2010). "More recently genistein was shown to bind to transthyretin and to have a beneficial effect as an inhibitor of transthyretin amyloidosis." (PMID 19319186, 2009). "For example it has been suggested that genistein acting in the micromolar range is able to bind to transthyretin and can have a beneficial effect as an inhibitor of transthyretin amyloidosis." (PMID 19319186, 2009). "Case series have described AL amyloidosis as being more prevalent in males and as occurring at a younger age than transthyretin-related amyloidosis." (PMID 20062619, 2009). "Familial (ATTR) Amyloidosis is possibly the most common form of a rare disease, a result of mutant transthyretin deposition in the affected organs." (PMID 20062619, 2009). "Biochemical and biophysical evidence confirms that iodine atoms can be an important design feature in the search for candidate drugs for TTR related amyloidosis." (PMID 19125186, 2009). "The largest series addressing Familial Amyloidosis noted a very low frequency of transthyretin amyloid samples cross reacting with light chain staining." (PMID 20062619, 2009). "The thyroid hormone and retinol transporter protein known as transthyretin (TTR) is in the origin of one of the 20 or so known amyloid diseases." (PMID 19125186, 2009). "Amyloidosis linked to wild type TTR appears to cause senile systemic amyloidosis (SSA), whereas most of the one hundred TTR mutants, already identified, result in familial amyloidotic polyneuropathy (FAP)." (PMID 19125186, 2009). "The pancreatictissue from the individuals with familial TTR-amyloidosis contained varyingamounts of amyloid, irregularly distributed in the exocrine parenchyma and surroundingconnective tissue." (PMID 18825272, 2008). "Senile amyloidosis is seen in those over the age of 80 and is due to deposition of normal or wild type of transthyretin." (PMID 20142933, 2008). "Similar to other types ofsystemic amyloidosis, most of the fibril protein in these amyloidoses isderived from the plasma pool and the major expression site of TTR is the liver." (PMID 18825272, 2008). "TTR is the major amyloidfibril protein in several systemic familial forms of amyloidosis and in theprevalent senile systemic amyloidosis." (PMID 18825272, 2008). "Previously proposed associations with poor prognosis in cardiac amyloidosis include reduced ejection fraction, low ECG voltages, increased left ventricular wall thickness on echo, and the type of amyloidosis (with worse prognosis in AL compared with TTR type)." (PMID 19032744, 2008).
amyloidosis (continued). "This is a characteristic for types of disease other than primary amyloidosis (AL) including secondary (AA), familial with genetically variant transthyretin (ATTR), amyloidosis associated with dialysis (Aβ2M), as well as Aβ and AIAPP forms." (PMID 16138931, 2005). "In contrast, ATTRwt amyloidosis arises from age-associated instability of WT TTR without genetic mutations." (PMID 41492466, 2026). "For this review, relevant studies were searched in PubMed/Medline (updated December 2024) using the following terms: amyloidosis; cardiac amyloidosis; transthyretin; ATTR; cardiomyopathy; stabilizer; siRNA; ASO; silencer; gene editing as well as the drug names." (PMID 41030053, 2026). "A relationship between greater reduction in circulating TTR and better clinical outcomes could be hypothesized based on data from other forms of amyloidosis." (PMID 41030053, 2026). "Transthyretin (TTR) amyloidosis is a systemic, progressive, and fatal disease." (PMID 42188091, 2026). "Pulmonary-dominant transthyretin (TTR) amyloidosis is an uncommon condition." (PMID 41909370, 2026). "Among amyloidosis patients, 21 had transthyretin and 3 had light-chain cardiac amyloidosis." (PMID 41590211, 2026). "First, a retrospective chart review was conducted for all patients with known transthyretin cardiac amyloidosis who attended the Cardiac Amyloidosis clinic at the Victorian and Tasmanian Amyloidosis Service (Australia) from 2014 to 2024 to identify those with a pacemaker implantation." (PMID 41857803, 2026). "The Transthyretin Amyloidosis Outcomes Survey (THAOS; NCT00628745) is a global, longitudinal observational registry study including patients with ATTR amyloidosis and asymptomatic TTR mutation carriers between 2007 and 2023." (PMID 40649158, 2025). "Wild-type transthyretin (ATTRwt) amyloidosis typically presents with restrictive cardiomyopathy." (PMID 40833310, 2025). "Besides its role in the pathogenesis of TTR amyloidosis (ATTR), a growing body of evidence points to a role of TTR in the development of another form of amyloidosis, namely Alzheimer’s disease (AD)." (PMID 39192044, 2025). "Hereditary transthyretin-mediated amyloidosis is treated with Patisiran." (PMID 39744758, 2025). "In the present study, we sought to investigate the evolution of renal parameters in patients diagnosed with ATTRv-N, defined as biopsy-proven or very likely direct kidney involvement by TTR amyloid deposits, recruited in 6 French referral centers for amyloidosis." (PMID 40630302, 2025). "ATTR (transthyretin) amyloidosis, whether hereditary or wild-type, most often presents with cardiac involvement or peripheral neuropathy in older adults—features not observed in our patient." (PMID 40700073, 2025). "However, the utilization of bone scintigraphy tracers facilitated the initial detection of transthyretin amyloidosis, which distinguishes the two types of amyloidosis." (PMID 40134993, 2025). "For example, AL amyloidosis patients might display positive uptake similar to TTR amyloidosis, necessitating detailed serum analysis to exclude AL cardiac amyloidosis before making a final interpretation." (PMID 41159134, 2025). "In contrast, wild-type transthyretin amyloidosis (wtATTR) is more common and is characterized by the absence of a mutation (pathogenic variant) in the TTR gene, the only associated gene to date." (PMID 39963604, 2025). "Sixty individuals (27 males, 45%) were heterozygous carriers of one of the five TTR variants but did not fulfill the diagnostic criteria for ATTRv amyloidosis: Ser77Tyr (n = 45), Val122Ile (n = 8), The60Ala (n = 2), Val30Met (n = 4), or Val32Ala (n = 1)." (PMID 39878313, 2025). "Due to the positive correlation of RASI with LV wall thickness in AL‐CM, the significant difference in RASI between AL‐CM and TTR‐CM might be generated at early stage of amyloidosis." (PMID 39873364, 2025).
amyloidosis (continued). "TTR amyloidosis is subdivided into two main categories: hereditary amyloidosis (h-ATTR), caused by genetic mutations in the transthyretin gene, and wild-type amyloidosis (w-ATTR), caused by the deposition of wild-type (normal) transthyretin, typically seen in older patients." (PMID 41024906, 2025). "As with all therapies for TTR amyloidosis, treatment response to tafamidis varies among patients, with approximately one-third of V30M ATTRv-PN treated with tafamidis showing complete cessation of disease progression, one-third exhibiting slowed progression, and one-third not responding." (PMID 40564999, 2025). "Our findings collectively open new avenues for research into the proteome alterations in amyloid diseases and elucidation of several key proteins that have the potential to be leveraged as biomarkers for V30M ATTRv-PN, including TTR itself, CP, APOE, and the complement pathway proteins such as C3." (PMID 40564999, 2025). "The FDA has approved the clinical application of CRISPR-based gene therapies for the treatment of sickle cell disease (SCD), β-thalassemia (TDT), transthyretin (TTR) amyloidosis, Leber congenital amaurosis type 10 (LCA10), human immunodeficiency virus (HIV), and Duchenne muscular dystrophy (DMD)." (PMID 39942646, 2025). "In addition, recent studies showed that CA possesses neuroprotective effects against transthyretin (TTR) amyloidosis by inhibiting pathological TTR fibril formation and reducing cytotoxicity from amyloid aggregates." (PMID 40932246, 2025). "All of these amyloidosis types could be clearly confirmed with varying relative highest abundances of TTR (ATTR1-2 to ATTR1-10), IGLL (ALλ1-2 to ALλ1-6), IGKL (ALκ1-1 to ALκ1-2), SAA (AA1-1 to AA1-3), and CALCA (ACal1-1 to ACal1-3)." (PMID 40701201, 2025). "Tafamidis and newer transthyretin stabilizers have redefined the prognosis of transthyretin amyloidosis, myosin inhibitors represent a breakthrough in hypertrophic cardiomyopathy, and structured surveillance has been recognized as essential in Takotsubo syndrome." (PMID 41440863, 2025). "Additionally, the stability of variant TTR and ERAD mechanisms play a role, as destabilized variants such as A25T can bypass ERAD with T4 chaperoning, leading to CNS-selective amyloidosis." (PMID 40898332, 2025). "hATTR-associated features such as amyloidosis were considerably more enriched in TTR carriers versus non-carriers (OR = 5.45, p<.0001) relative to more common features, such as heart failure (OR = 1.43, p<.0001)." (PMID 41282679, 2025). "A phase 1 study addressing transthyretin amyloidosis utilized a dosage of 0.3 mg/kg to patients, resulting in the expression of Cas9 and the delivery of its single guide RNA to knock out the transthyretin gene, representing a potential treatment for this disease." (PMID 40621603, 2025). "Compared to other TTR variants, TTR G83R may more easily escape the ERQC system, consequently leading to amyloid deposition in the vitreous cavity." (PMID 40666113, 2025). "In contrast, when cardiac involvement is due to TTR amyloidosis, as in this case, treatment is directed toward the amyloid itself, while the malignancy may not require immediate therapy." (PMID 41024906, 2025). "Wild-type amyloidosis is associated with ATTR, and the transthyretin protein produced is not mutated." (PMID 38829477, 2025). "In wild-type ATTR amyloidosis (ATTRwt), an age-related condition previously known as “senile systemic amyloidosis”, the amyloid fibrils consist of normal, non-mutated TTR proteins." (PMID 40649158, 2025). "However, amyloidosis was strongly suspected due to myocardial wall thickening, and endomyocardial biopsy showed amyloid deposits specifically immunolabeled with an anti-TTR antibody." (PMID 40429804, 2025).
amyloidosis (continued). "The most common TTR mutant, V122I (p.V142I), is notably prevalent among African-Americans (3.0–3.9%) resulting in a median survival of 25.6 months after diagnosis, which is slightly shorter than that in ATTRwt amyloidosis (43–75 months)." (PMID 40429804, 2025). "Ultimately, Sanger sequencing analysis revealing wild-type transthyretin amyloidosis (wtATTR) without a TTR gene mutation." (PMID 39963604, 2025). "Anti-TTR siRNAs have been developed as successful drugs to treat TTR amyloidosis." (PMID 40386915, 2025). "Variant transthyretin amyloidosis with polyneuropathy (ATTRv-PN) and cardiomyopathy (ATTRv-CM), formerly known as familialamyloidotic polyneuropathy(FAP), is a severe, progressive disorder caused by mutations in thetransthyretin(TTR) gene." (PMID 40541194, 2025). "The predominant types are immunoglobulin light chain and transthyretin (ATTR) amyloidosis." (PMID 41367026, 2025). "Dozens of proteins that are normally soluble may form aggregates that are traditionally associated with specific diseases – e.g. tau tangles and amyloid plaques with Alzheimer’s Disease, and transthyretin deposits with transthyretin amyloidosis." (PMID 39713930, 2024). "CA is classified as originating from either transthyretin (ATTR) or light chain (AL) amyloidosis." (PMID 39540049, 2024). "Eplontersen (WainuaTM) is indicated for the treatment of transthyretin-mediated amyloidosis." (PMID 38338330, 2024). "While the cross interaction of compounds with RBP4 may have the capacity to reduce amyloidosis by restricting RBP4 to interact with Transthyretin." (PMID 39446901, 2024). "Patisiran is a first-of-its kind RNA interference (RNAi)-based therapy designed to reduce levels of both WT and mutant transthyretin (TTR) for the treatment of patients with hereditary transthyretin-mediated amyloidosis, a congenital neurological and cardiac disorder." (PMID 38992695, 2024). "Non-invasive diagnosis of amyloid transthyretin (ATTR) cardiac amyloidosis using planar scintigraphy and single-photon emission computed tomography-computed tomography (SPECT-CT) with [99mTc]Tc-3,3-diphosphono-1,2-propanodicarboxylic acid ([99mTc]Tc-DPD) has high specificity and sensitivity." (PMID 39224107, 2024). "Wild-type transthyretin (ATTRwt) amyloidosis is a progressive protein-misfolding disease characterized by deposition of amyloid predominantly in ligaments, tendons and the myocardium, causing carpal tunnel syndrome, spinal stenosis and ATTR cardiomyopathy (ATTR-CM)." (PMID 39115713, 2024). "Genetic testing revealed no TTR gene mutations; therefore, the patient was diagnosed with ATTRwt amyloidosis." (PMID 38888709, 2024). "The absence of correlation between neurofilament(+) nerve fiber area and TTR(+) amyloid area in this study prompted us to test the vascular hypothesis, that is, microangiopathy might serve as an add‐on mechanism contributing to nerve degeneration in ATTRv." (PMID 37902278, 2024). "Genetic testing was negative for transthyretin mutation, confirming wild-type transthyretin amyloidosis." (PMID 39703588, 2024). "Wild-type transthyretin (ATTRwt) amyloidosis is by far the most prevalent form." (PMID 38256502, 2024). "In our first case, the time elapsed to establish a diagnosis of transthyretin amyloidosis from the onset of symptoms was 7 years, through the retrospective analysis of the clinical history of a patient with a mixed phenotype treated at Manuel Ygnacio Monteros-IESS Loja General Hospital." (PMID 39449414, 2024). "They specifically recognized TTR amyloid in the heart and other affected tissue." (PMID 39338387, 2024). "Wild-type transthyretin-mediated amyloidosis (ATTRwt amyloidosis) is a non-hereditary, progressive, debilitating, fatal disease caused by the accumulation of misfolded wild-type transthyretin (TTR) amyloid fibrils." (PMID 39516862, 2024). "This may be due to amyloidosis referring to a heterogeneous group of disorders or to TTR amyloidosis being underdiagnosed." (PMID 38523305, 2024).